IFNL1 (interferon lambda 1)
Diseases named in the same sentence as IFNL1 in open-access papers (continued):
Sharing a sentence is not in itself a finding about the gene and the disease.
infection (86 papers, 2010 to 2026). The state of being infected such as from the introduction of a foreign agent such as serum, vaccine, antigenic substance or organism. "Only weak upregulation of IFNL1 mRNA expression was observed after infection of pericytes by both RVFV strains." (PMID 39345143, 2024). "To provide sufficient material to make measurements with statistical rigor, we used flow cytometry to concurrently measure the presence of the NS segment, and the M segment in an NS1stop infection of IFNL1 reporter cells." (PMID 37068114, 2023). "At a genome-corrected MOI of 0.1, ∼2.7% of cells were positive for the IFNL1 reporter after infection with the low-defective NS1stop." (PMID 37068114, 2023). "IFNB1 expression was also elevated following infection; however, IFNL1, IFNL2, and IFNL3 expression clearly dominated the innate immune response." (PMID 36268025, 2022). "As expected, HRV16 infection of epithelium differentiated in control conditions resulted in a marked induction of IFNs (mean 200-fold for IFNL1), and most of the analyzed antiviral effectors with ISGs being the top group upregulated (10 to 100-fold)." (PMID 34140575, 2021). "As measured by the expression of the influenza viral protein M1 and M2, interferon beta led to a robust inhibition of infection, while IFNL1 led to more modest inhibition." (PMID 34899695, 2021). "In contrast to the minimalincreases observed during WT MERS-CoV infection over mock-infected cells,MERS-ΔNS4a or MERS-ΔNS4ab infection resulted in significantly elevatedlevels of IFNL1 mRNA and representative ISG OAS2 andIFIT2 mRNAs." (PMID 30914508, 2019). "In contrast to SeV and SINV, which robustly induced IFN and ISGexpression by 12 hpi, MERS-CoV induced little IFNL1 orIFNB expression throughout a 36-h course of infection." (PMID 30914508, 2019). "When compared with the chicken H7N9-CK, the human H7N9-HU induced a stronger TNF-α response at 12 and 24 h post-infection, but a weaker IFNL1 response between 12 and 48 h post-infection." (PMID 26975414, 2016). "Conversely, the mean level of IFNL1 was significantly lower for H7N9-HU (39-fold) than that of H7N9-CK (55-fold) at 48 h post-infection (P = 0.0005)." (PMID 26975414, 2016). "As IFNL1 plays an important role in the immune system, we assume that the protective features are involved in a more resistant immune response to subclinical infection processes." (PMID 39408633, 2024). "However, the level of IFNL1 was lower for H7N9-HU than that of H7N9-CK at 48 h post-infection (P < 0.001)." (PMID 26975414, 2016). "Accordingly, the transcription factor IRF1, reported to be essential for MAVS-mediated IFNL1 expression, was detected in nuclear extracts as early as 6 h post infection with RSV-HD while it remained at basal levels in cells infected with RSV-LD or mock infected." (PMID 26336095, 2015). "Notably, IRF1 knockdown was incomplete and the reduced amount of IRF1 protein observed upon infection with RSV-HD infected si-1 treated cells likely explains the low level of expression of IFNL1 observed upon infection of the knockdown cells." (PMID 26336095, 2015). "Lambda interferons (IFNLs) include IFNL1/interleukin-29 (IL-29), IFNL2/IL‐28A, IFNL3/IL‐28B, and IFNL4, all of which are critical for a balanced antiviral response in the respiratory tract for optimal protection against infection and minimizing associated damage." (PMID 38703289, 2024). "Interestingly, ZIKVBR infection caused a significant increase in IFNL1 secretion by trophoblasts from non-affected twins, whereas in trophoblasts from CZS-affected twins no significant increase was observed." (PMID 32745093, 2020). "In contrast, infection of A459ACE2 cells with NL63 robustly induced IFNB and IFNL1 as well as IFIT1 and OAS2 by 48 hpi." (PMID 41369222, 2026). "IP-10, IFNL1, IFNB1, and CASP1 gene expressions were significantly induced by Delta infection, whereas Remdesivir treatment prevented it efficiently with levels similar to non-infected cultures." (PMID 40142465, 2025).
infection (continued). "Similar to our findings made by EPO of HepG2/C3A cells, expression of ISG15, IFNL1, and an additional ISG, IFIT1, peaked on day 5 post-ΔORF2 infection and decreased again to a similar level as WT on day 7 post-infection." (PMID 40982567, 2025). "Infection of wild type (WT) A549 cells with Sendai virus (SeV) or Zika virus (ZIKV) resulted in robust IFN-I (IFNB1) and IFN-III (IFNL1) transcription and activation of both IRF3-dependent (ISG54) and NF-κB-dependent (NFKBIA) genes." (PMID 38001254, 2024). "In our study, patients with mild COVID had a rapid production of IFNL1 and IFNL2, which although decreasing over time, was still detectable 2 months post-infection." (PMID 38953458, 2024). "By RT-PCR analysis of cell lysates at 24 hours post-infection (h.p.i.)we observed the robust induction of IFNA1, IFNB and IFNL1." (PMID 36439115, 2022). "Infection with SARS-CoV-2 strongly induced the expression of type I (IFNB1) and type III (IFNL1) IFNs as well as several ISGs, although peak expression levels resulting from SARS-CoV-2 infection were lower than after H1N1 infection." (PMID 35840680, 2022). "Infection of PCLS resulted in the robust secretion of IFNγ, followed by IFNL1, and IFNα2, while secreted IFNβ was unchanged (IFNγ>>IFNL1> IFNα2>> IFNβ)." (PMID 34899695, 2021). "Here, we corroborate these findings in Calu-3 cells using an unbiased genome-wide methodology showing that antiviral cytokines (IFNL1-3, IFNB1, CCL5, CXCL11 and IL6) are restricted in translation at 24 h post infection." (PMID 33806254, 2021). "Conversely, expression of IE1dl410-420 led to a marked increase in infection-related induction of the IFNB1, IFNL1, CCL5, TNF and PML genes." (PMID 32365141, 2020). "Early in the infection (<8 hpi), the rate of IFNL1 induction depends linearly on cellular MOI, such that cells with higher levels of virus input have higher rates of IFNL1 induction than cells with lower levels of virus input." (PMID 33064776, 2020). "IE1cc172-176 expression resulted in significantly reduced induction of transcripts from the IFNB1, IFNL1, CCL5 and TNF genes relative to the wild-type protein following infection." (PMID 32365141, 2020). "Unlike H5N1, H1N1 induced significantly lower levels of IL-6, MCP-1 and TNF-α at 24 h post-infection; and MCP-1, TNF-α, IL-10, IFNL1 and IFN-β at 48 h post-infection when compared with H7N9-CK or H7N9-HU." (PMID 26975414, 2016). "On the contrary, the levels of IFNL1 and MCP-1 were lower in Calu-3 cells infected with H7N9-HU than that of H7N9-CK at 48 h post-infection." (PMID 26975414, 2016). "However, the comparatively lower ΔORF2 RNA level after internalization and the significant decrease until day 7 compared to WT RNA suggested a relatively stronger induction of IFNL1 and ISG15 expression in ΔORF2 infection." (PMID 40982567, 2025). "They observed that after infection withSARS-CoV-2, endothelialcells from infected lung-on-chips showed significant upregulationof TNF-α, IL6, and IFN-β and more modest increase ininterferon-λ1 (IFNL1) and IFNL3 expression." (PMID 38559954, 2024). "Furthermore, significant variations were observed in the levels of IFNL1, IL1A, IL6, and CCL2 interferons or other cytokines in cell supernatant through ELISA when comparing these two infection conditions." (PMID 37515115, 2023). "We further investigated the possible differences in host defense pathways by RNA-seq analysis and found an increase in some key host defense transcripts, such as IFNL1, IFNL3, CXCL10, and CXCL11, in response to infection with recent EV-D68 isolates compared to Fermon." (PMID 37376591, 2023). "In striking contrast, IRF3 KD had an initial effect on the type III IFN, IFNL1 after 10 h of infection, but did not affect its later expression at 24 h." (PMID 37564646, 2023).
infection (continued). "While infection with either virus triggered robust transcriptional interferon responses, including induction of type I (IFNB1) and type III (IFNL1) interferons, markedly lower levels of interferons and inflammatory proteins (IL-6, IL-8) were released following SARS-CoV-2 compared to H1N1 infection." (PMID 35840680, 2022). "Thus, many immune related proteins are elevated at infection in both cases, such as chemokine ligand 10 (CXCL10), interferon gamma (IFNG), interferon lambda 1 (IFNL1) and chemokine ligand 8 (CCL8)." (PMID 34844191, 2021). "At 24 and 48 h post-infection, the predominant interferons induced in the primary airway cells at the mRNA level were IFNβ, IFNL1, and IFNL2/IFNL3 (qRT-PCR cannot distinguish these isoforms), with IFNL1 and IFNL2/3 being the most upregulated." (PMID 34899695, 2021). "We observed increased IFNB1, IL29/IFNL1, IL28A/IFNL2, IFNL3, RSAD2, and CXCL10 post infection." (PMID 33409274, 2020). "In Perth09-infected cells, IFNL1 (type III IFN) transcription was roughly 20-fold more frequent compared with Cal07, indicating a significant difference in the ability of the host to initiate an IFN response to infection by these two strains." (PMID 32614923, 2020). "We also quantified in the hiPSC-derived trophoblasts the secreted levels of type I (IFNA2), type II (IFNG) and type III (IFNL1) IFNs produced by these cells in the absence of virus or after infection with ZIKVBR and culture for 48 h or 96 h." (PMID 32745093, 2020). "S. epidermidis isolated from healthy individuals (N1, N2, N3, and N4) significantly elevated the levels of IFNL1 and IFNL2/3 mRNA in NHNE cells starting at 8 h after treatment, with maximum levels observed 24 h after infection (IFNL1 6.4 × 103, IFNL2/3 1.1 × 104)." (PMID 31146794, 2019). "When we examined the expression levels of inflammatory cytokines and interferons, we found that the expression levels of interleukin-1 beta (IL-1β), interleukin-6 (IL-6), tumor necrosis factor (TNF-α), interferon beta (IFN-β), and interferon lambda-1 (IFN-λ1) were not altered by MPXV infection." (PMID 41542170, 2025). "Upon infection, expression of IFNL1 and IFNL2 but not type I IFN in P. alecto." (PMID 39968756, 2025). "However, later in the infection (>8 hpi), the rate of IFNL1 induction does not depend on virus input." (PMID 33064776, 2020). "Considering the rapidity by which translational repressor 4E-BP1 is inactivated (within an hour) and the ability of RSVA2 to negate the effects of MEKi on ISGs (i.e. IRF1), these events might partly explain the absence of positive modulation of IFNL1 gene following RSVA2 infection." (PMID 31319869, 2019). "However, we did not detect induction of IFNL1 under any of these conditions, suggesting that other factors released to the medium during infection may be responsible for the broad pattern of expression identified by single-cell analysis." (PMID 31375585, 2019). "Analysis of interferons (IFNs) and IFN stimulated genes (ISGs) 24 h post-HRV16 infection revealed induction of IFNB1 and IFNL1 genes by HRV16 but not UV-HRV16." (PMID 36366528, 2022). "The induction of IFNB1 and IFNL1 expression was readily observed in SARS-CoV-2–infected tissues at 37°C, with no significant change observed during infection at 40°C relative to mock-treated samples." (PMID 34932557, 2021). "Upon in vitro infection with ZIKVBR, a marked induction of mRNA expression of IFNB1, IFNL1, IFNL2 and IFNL3 genes but not of IFNE was observed." (PMID 32745093, 2020). "After 48 h in culture without infection, hiPSC-derived trophoblasts from both CZS-affected and non-affected twins were able to secrete IFNA2 and IFNG, whereas IFNL1 was not detectable." (PMID 32745093, 2020).
infection (continued). "Infection of the human lung epithelial cell line A549 with RSV-HD resulted in the expression of IFNL1 (also known as IL-29), IFIT1 (also known as ISG56) and IFNB1; no expression of these genes was detected upon infection with RSV-LD, despite higher levels of viral replication (RSV G expression)." (PMID 26336095, 2015).
tumor (13 papers, 2012 to 2024). "Three activated UPRs associated with immune activation were unique to CPA/6d-treated GL261(B6) tumors: EIF2AK2, IFNL1 and MAVS, while the two activated UPRs specific to GL261(scid) tumor responses, DMD and SPARC, have glial cell-related functions:." (PMID 27515027, 2016). "As new immunotherapies and targeted therapies are revealed, our findings suggest value in further investigations into a panel of personalized tumor markers, which may include proteins with therapeutic relevance such as FOLR1, KRT19, KLK6, PARP-1, TROP2, and IFNL1." (PMID 34868557, 2021).
cancer (9 papers, 2012 to 2025). A tumor composed of atypical neoplastic, often pleomorphic cells that invade other tissues. "We found that IFNA1 and IFNL1 gene transcripts resulted negligibly expressed across the pan-cancer dataset when compared to other immunosuppressive and pro-inflammatory cytokines such as TGFB1/2, PTGES2, IL1A, IL1B, IL6 and CSF1." (PMID 38239354, 2023). "Thus, we stimulated each cancer cell line with HT-DNA and measured expression of IFNL1, IFNL2, and IFNB1 after 2, 6, 10 and 20 hours." (PMID 40012911, 2024). "Interestingly, IFNL1 expression was significantly upregulated by both doxorubicin and cisplatin in three of the cancer cell lines and did not seem to correlate with cGAS protein expression." (PMID 40012911, 2024).
renal disorder (1 paper, 2016). "IFN-lambda 1 (IFNL1, also known as IL29), a type III IFN, has been proposed previously as a key molecule in renal disorder and arthritic progression in SLE." (PMID 27846842, 2016).
IFNL1 also shares sentences with these, for which no sentence is quoted: systemic lupus erythematosus (5 papers); melanoma (4); Insulin resistance (3); liver disease (3); osteoarthritis (3); periodontitis (3); uveitis (3); anemia (2); atherosclerosis (2); autoimmune thyroid disease (2); Autoimmunity (2); bacterial infections (2); breast carcinoma (2); cardiovascular disease (2); chronic periodontitis (2); diabetes (2); glioma (2); Hepatitis (2); hepatitis C (2); pancreatic cancer (2); pneumonia (2); psoriasis vulgaris (2); systemic sclerosis (2); type 2 diabetes (2); Arthritis (1); atopic dermatitis (1); autoimmune gastritis (1); autoimmune hepatitis (1); brucellosis (1); chronic rhinosinusitis (1).
A further 40 diseases each share a sentence with IFNL1 in 1 paper.